RNU4-10P (RNA, U4 small nuclear 10, pseudogene)
Gene: Small nuclear RNA gene on chromosome 13 (73,191,528 to 73,191,667, forward strand). Ensembl gene ENSG00000201253.
Homologues: Orthologues: chimpanzee U4 (99% identical), macaque U4 (95% identical). Paralogues in human: RNU4-49P (84% identical), RNU4-79P (81% identical), RNU4-32P (81% identical), RNU4-17P (80% identical), RNU4-81P (79% identical), RNU4-50P (79% identical), RNU4-28P (77% identical), RNU4-51P (76% identical), RNU4-83P (75% identical), RNU4-90P (74% identical), RNU4-52P (74% identical), RNU4-15P (73% identical), and 81 more.